RNVU1-23 (RNA, variant U1 small nuclear 23)
Synonyms: RNU1-92P
Gene: Small nuclear RNA gene on chromosome 1 (143,720,510 to 143,720,644, reverse strand). Ensembl gene ENSG00000252826.
Gene Ontology:
Molecular function: pre-mRNA 5'-splice site binding
Biological process: mRNA 5'-splice site recognition
Cellular component: U1 snRNP
Homologues: Orthologues: chimpanzee U1 (99% identical), macaque U1 (79% identical), dog U1 (68% identical), guinea pig U1 (68% identical), pig U1 (66% identical). Paralogues in human: RNU1-155P (90% identical), RNU1-89P (74% identical), RNVU1-1 (73% identical), RNU1-1 (73% identical), RNU1-148P (73% identical), RNU1-2 (73% identical), RNU1-27P (73% identical), RNU1-28P (73% identical), RNU1-3 (73% identical), RNU1-4 (73% identical), RNVU1-18 (73% identical), RNVU1-28 (73% identical), and 134 more.